CD80 (CD80 molecule)
Diseases named in the same sentence as CD80 in open-access papers (continued):
Sharing a sentence is not in itself a finding about the gene and the disease.
Sepsis (continued). "This demonstrated the emergence of impaired CD80+CD86+ cells and the reduced T cell ability to stimulate after the induction of sepsis in aged animals." (PMID 33673691, 2021). "The suppressed expression of CD80, CD86, and MHC-II was reversed by inhibiting cerebral HMGB1 at 48 h after sepsis." (PMID 34512319, 2021). "Both SP DCs and MLN DCs increased the activation markers, such as MHC class II, CD80, or CD86 during sepsis." (PMID 31323786, 2019). "Mature DCs activate T cells through costimulatory molecules CD80 and CD86 and then are reprogrammed during sepsis to a tolerogenic state." (PMID 30069485, 2018). "In murine studies of sepsis, an important role for CD80 and CD86 antigens in the response to sepsis has been established." (PMID 25302303, 2014). "Upregulation of coinhibitory molecules, PD-L1 and PD-1, and downregulation of positive costimulatory molecules, CD28, CD80, and CD86, are the features of sepsis-induced immunosuppression, reversal of which will improve the survival of septic mice." (PMID 24891762, 2014). "We next sought to determine the relative contributions of CD80 and CD86 to mortality and inflammatory cytokine production in polymicrobial sepsis." (PMID 19672303, 2009). "In conclusion, our data describe a differential role for CD80 and CD86 in regulation of inflammation in the innate immune response to sepsis." (PMID 19672303, 2009). "Together suggesting CD28, through either CD80 or CD86 is capable of mediating the inflammatory response and lethality of polymicrobial sepsis." (PMID 19672303, 2009). "Another potential reason for the prominent effect for CD80 in innate immunity, centers on the differential expression of CD80 and CD86 in sepsis." (PMID 19672303, 2009). "Functional markers such as CD40, CD80, CD86, and MHC-II were significantly upregulated by DCs in animal sepsis models during the initial phase of sepsis, which is essential for the activation of T cells, while DCs downregulated the expression of surface molecules at the late stage of sepsis." (PMID 38816685, 2024). "Macrolides increased CD80 but not HLA-DR in patients with chronic sinusitis, while clarithromycin increased HLA-DR in patients with pneumonia and sepsis and increased CD86 in patients with ventilator-associated pneumonia and sepsis." (PMID 39596729, 2024). "CD28 is a T cell costimulatory receptor which, upon ligation with CD80/CD86, transmits a costimulatory signal important for T cell activation, proliferation, and pro-inflammatory responses, making it a potential target for sepsis immunomodulatory therapy." (PMID 38633258, 2024). "The ratio of DCs expressing MHC-II, CD86, and CD80, the mRNAs level of dendritic cells expressing TNF-α and IL-12, and the level of DC-mediated T-cell proliferation were all decreased, both in vivo and in vitro during sepsis, when PINK1 was knocked out." (PMID 36809929, 2023). "Furthermore, we labeled M1-LIKE (CD80+) and M2-LIKE (CD163+) and the data indicated that M2-LIKE cells were significantly higher than M1-LIKE cells in the peripheral blood of sepsis patients." (PMID 36845133, 2023). "It was found that the percentages of MHCII, CD40, CD80, and CD86 on surface of DCs obviously increased in the sepsis-induced ALI group when compared to the control and GTS-21-positive control mice group, and the increase in MHCII, CD40, and CD86 was reduced through GTS-21 intervention." (PMID 35125962, 2022). "The expressions of CD80, CD86, and MHC-II were all increased at 24 h after the induction of sepsis." (PMID 34512319, 2021). "The differential changes in CD80 and CD86 expression on CD11c+ DCs during the early and late phases of our sepsis model suggest that CD80+ and CD86+ are differentially modulated due to sepsis, so we determined whether SIRT1 inhibition balances this pattern." (PMID 30069485, 2018).
Sepsis (continued). "Consequently, the goals of this study were to determine the individual contribution of CD28, CD80 and CD86 to the inflammatory response in murine sepsis, and to better correlate expression of these molecules with outcome in humans with sepsis and septic shock." (PMID 19672303, 2009). "Additionally, CD80 and CD86 cell surface markers expressed by activated monocytes/macrophages have a differential role in the regulation of inflammation, especially in the innate immune response to sepsis." (PMID 37761018, 2023). "The ability of CD28 to regulate inflammation in the innate immune response to sepsis is consistent with prior reports documenting CD28 expression on PMNs and the ability of CD28, either soluble or in PMN lipid rafts, to induce NF-κB and pro-inflammatory cytokine production via CD80/CD86." (PMID 19672303, 2009). "Finally, we sought to expand our previously reported data and determine whether differential expression of CD80 and CD86 occurred in humans with sepsis and if expression levels could serve as biomarkers for outcome." (PMID 19672303, 2009). "In addition, sepsis did not cause the change of CD40 and CD80 in the lung until 7 d after CLP." (PMID 25821827, 2015). "In an in vitro model of sepsis-related ARDS, co-culture with transgene-inactive and transgene-active HSD-1 tMSCs had no impact on AM surface expression of C206, CD163, CD80, SIRPα or Mer." (PMID 39036559, 2024). "On the other hand, the expressions of CD80 on both SP DCs and MLN DCs, and those of CD86 on SP DCs, were shown to be increased by sepsis; however, neither marker was significantly higher on MLN DCs compared to SP DCs in septic mice." (PMID 31323786, 2019). "Finally, the improved survival with anti-CD80 as opposed to anti-CD86 confirms the results obtained with the knockout mice and the ability of anti-CD80 to rescue mice when given after the onset of sepsis suggests this is a potential therapeutic target as well." (PMID 19672303, 2009).
rheumatoid arthritis (40 papers, 2008 to 2025). A chronic, systemic autoimmune disorder characterized by inflammation in the synovial membranes and articular surfaces. "Due to its CD80-suppressing ability, triptolide plays an important role in rheumatoid arthritis treatment, and CD80 expression is linked to the frequent relapse of the group of minimal change diseases, a form of chronic kidney disease." (PMID 39795863, 2024). "Hence, a specific antibody targeting MCD-caused CD80 expression should be developed instead of using a repurpose drug of rheumatoid arthritis (abatacept)." (PMID 33506028, 2021). "In rheumatoid arthritis, pro-inflammatory CD80+ macrophages sustain immune imbalance; EVs engineered to deliver methotrexate reprogram them toward anti-inflammatory phenotypes, enhance Treg differentiation, and suppress Th1 responses." (PMID 41368630, 2025). "For example, Lin and colleagues illustrated that IL-26 expression was increased in the synovium of rheumatoid arthritis and that IL-26 promoted macrophage differentiation from CD80+ M1 macrophages, concomitantly activating the NF-κB pathway." (PMID 39511608, 2024). "CTLA4-Ig abatacept is an inhibitor that targets CD80 (also known as B7.1) and is currently used for rheumatoid arthritis (RA)." (PMID 32420329, 2020). "The CD80/CD86 levels on the surface of the memory B cells in the blood of 18 patients with rheumatoid arthritis (RA) were detected using immunofluorescence staining." (PMID 32228715, 2020). "Based on previous studies, CXCR3 is absent in normal naïve B cells but is upregulated on malignant B cells while CD80 plays an important role for the activation of autoreactive T cells during rheumatoid arthritis." (PMID 30150281, 2018). "Abatacept is the first in a class of agents for the treatment of rheumatoid arthritis (RA) that selectively modulates the CD80/CD86:CD28 co-stimulatory signal required for T-cell activation." (PMID 20398273, 2010). "Moreover, it is capable of increasing the surface expression of co-stimulatory molecules, such as CD54, CD40, and CD80, and it also enhances B-cell proliferation and inhibits neutrophil apoptosis in rheumatoid arthritis." (PMID 37373251, 2023). "Using a longitudinal cohort of n = 38 rheumatoid arthritis (RA) patients treated with abatacept, we tested whether these COVID-19-related processes are modified during CD80/86 axis blocking." (PMID 34075090, 2021). "Research findings highlight Abatacept’s effectiveness in rheumatoid arthritis (RA) treatment, showcasing its ability to modulate the expression of CD80/CD86 in peripheral blood B cells." (PMID 38398810, 2024). "Abatacept (ABA) is the first and only one of biological disease-modifying anti-rheumatic drugs (bDMARDs) for rheumatoid arthritis (RA) that inhibits T lymphocyte activation by binding to CD80/86, thereby modulating its interaction with CD28." (PMID 33184461, 2020). "The biologic abatacept has traditionally been used for the treatment of rheumatoid arthritis (RA), where it acts as a T-cell inhibitor by binding to CD80 (B7-1) and CD86, thus blocking the costimulatory receptor CD28." (PMID 26490951, 2016). "Abatacept, a T-cell selective co-stimulation modulator specifically binding to CD80 and CD86, was approved for use in rheumatoid arthritis (RA) with good efficacy in clinical application." (PMID 35957855, 2022). "CTLA-4-Ig that binds to CD80 and CD86 and has an inhibitory effect on the CD80/CD86–CD28 costimulation pathway is clinically effective in treating rheumatoid arthritis, and has also been shown to protect against experimental atherosclerosis." (PMID 34945203, 2021). "For rheumatoid arthritis (RA), three JAK inhibitors and a range of bDMARDs are approved, including those targeting TNFα, IL-6, IL-1β, B cells (CD20), and T cells (CD80/CD86)." (PMID 34290741, 2021). "Recombinant CTLA4-Ig has been developed and approved for rheumatoid arthritis and focal segmental glomerulosclerosis (FSGS) with CD80+ podocytes." (PMID 32512831, 2020).
rheumatoid arthritis (continued). "Abatacept, a CTLA4-Ig fusion protein, attenuates T cell activation by inhibiting the CD80/CD86–CD28 costimulatory pathway that is required for the proper T cell activation and thus displays beneficial effects in the treatment of rheumatoid arthritis (RA)." (PMID 29259723, 2017). "RANKL expression was accentuated in CD80+CD86+ B cells, a highly activated B-cell subset more abundantly observed in patients with rheumatoid arthritis." (PMID 26980135, 2016). "Abatacept (ABA) is a fusion receptor protein containing the CTLA-4 domain that prevents the activation of naïve T cells by binding the CD80 and CD86 molecules expressed on the surface of dendritic cells, indicated for the treatment of moderate to severe rheumatoid arthritis (RA)." (PMID 27098382, 2016). "Indeed, several studies reported an overall decrease in peripheral Tregs in kidney transplant recipients or rheumatoid arthritis patients treated with Nulojix® or Orencia®, which are CTLA4-Ig molecules binding CD80/86 and preventing CD28-mediated costimulation." (PMID 24376655, 2013). "Abatacept, a CTLA4-Ig fusion protein attenuates T cell activation by inhibiting the CD80/86-CD28 costimulatory pathway that is required for the proper T cell activation and thus displays beneficial effects in the treatment of rheumatoid arthritis (RA)." (PMID 29259723, 2017).
Autoimmunity (38 papers, 2005 to 2025). The occurrence of an immune reaction against the organism's own cells or tissues. "In several NSCLC cells, the mRNA expression of CD80/CD86 was detected in normal tissues, risking autoimmunity reactions; hence, new strategies are encouraged to overcome this risk by using CD80/CD86 CAR-T cells and enhancing its selectivity." (PMID 35814023, 2022). "In line with this, it was demonstrated that the disruption of PD-L1/CD80 cis binding by CD80 antibodies can alleviate autoimmunity due to the accessibility of the PD-1/PD-L1 interaction." (PMID 39062968, 2024). "But after three months, it was shown that the CD80:CD28/CTLA-4 pathway was hindered by increased production of IL-10, resulting in impeded production of CD80-induced IL-2, which plays a key role in lymphocyte expansion and the development of autoimmunity." (PMID 37946301, 2023). "CD69 has been identified as a B cell marker associated with MS whereas CD80 and CD86 are costimulatory molecules that are involved in immune regulation and B cells expressing CD80/CD86 have been shown to drive pathogenesis in autoimmunity." (PMID 36389698, 2022). "It has been suggested that CD86 is more important than CD80 in mediating resting T-cell activation by APCs and is essential for autoreactive T-cell activation and development for autoimmunity." (PMID 26209442, 2015). "Despite their largely overlapping functions in T cell activation and immune upregulation in autoimmunity, CD80 and CD86 on APCs also play additional individually distinct roles, which cannot be substituted for by the other." (PMID 24472094, 2014). "In addition, CD21lo B cells derived from patients with autoimmunity can serve as antigen presenting cells, as these cells express high levels of CD80, CD86 and HLA-DR." (PMID 36591307, 2022). "It is therefore important to understand that some RA preparations may have the desirable CD80 enhancement effect for cancer patients, whereas for autoimmunity patients RA preparations that have the biological effects of CD80 reduction are useful." (PMID 28337449, 2017). "Once a T cell is activated, CTLA-4 (CD28 homolog) is expressed on its surface to block the costimulatory signal through its greater affinity for CD80/86, playing an important role in self-tolerance and therefore limiting autoimmunity under normal homeostatic conditions." (PMID 27472273, 2016). "B cell-expressed CD80/CD86 has been shown to drive pathogenesis in autoimmunity." (PMID 24472094, 2014). "In contrast, studies have shown that DC treatment with proinflammatory cytokines are not sufficient to promote functional T helper immunity, while other studies have shown that Poly I∶C treatment can promote autoimmunity, only when islet cells are engineered to express CD80." (PMID 21931625, 2011). "Furthermore, it was suggested that an increase in CD80 on a subpopulation of activated memory B cells may be central to the development of autoimmunity." (PMID 36389698, 2022). "Abatacept inhibits the CD80/CD86:CD28 costimulatory signal required for full T cell activation and as such may alter the immune responses to tumors, as well as dampening pathogenic autoimmunity." (PMID 31703717, 2019). "The remarkable therapeutic efficacy of anti‐CD80/CD86 mAbs in preventing immune activation post‐Treg depletion raised the possibility that blockade of the delivery of co‐stimulatory signals may be used to treat ongoing autoimmunity secondary to complete deletion of Treg or dysfunctional Treg." (PMID 40346769, 2025). "In summary, our results demonstrate that the CD73, CD80 and PD-L2 markers, first identified in immunised WT mice, can distinguish different MBC subsets also in autoimmune mouse models, where the MBC3 subset is dominant." (PMID 36936947, 2023). "Abatacept, on the other hand, directly targets B cells by decreasing the expression of CD80/CD86, thereby offering a potential therapeutic approach for treating B cell-mediated autoimmunity." (PMID 38041172, 2023).
Autoimmunity (continued). "In the nonobese diabetic (NOD) mouse model, wherein CD28 or its ligands (CD80 [B7-1] and CD86 [B7-2]) have been knocked out, the number of natural Tregs (nTregs) decreased significantly, resulting in accelerated autoimmunity in mice." (PMID 37828948, 2023). "TLR9 ligation enhanced dendritic cell activation upregulating CD40 and CD80 expression, promoting systemic anti-MPO autoimmunity and T cell recall responses and exacerbating kidney injury." (PMID 36674855, 2023). "Other studies reported that DT-mediated depletion of Foxp3+ cells in DEREG mice induced increased division of DC and precursor DC in lymphoid organs and up-regulation of CD80, CD86 and CD40 in the context of autoimmunity." (PMID 36846549, 2022). "If Tregs use OX40 or CTLA-4 to suppress autoimmunity and induce T cell disappearance, the two molecules bind the ligands, OX40L or CD80/86, respectively, before Dsg3H1-Rag2−/− T cell disappearance." (PMID 34848535, 2021). "Consistently, ablation of B7/CD28 signalling in CD80/CD86 knock-out mice or clinically with CTLA-4Ig (abatacept) has been shown to impair T cell regulation and lead to aggressive secondary autoimmunity." (PMID 32580776, 2020). "The CTLA-4 receptor is located on the surface of effector T lymphocytes and interacts with CD80/CD86 (B7-1 or B7-2) on CTLA-4 antigen-presenting cells to induce T cell rest, preventing overactivation of the T cell system in autoimmunity." (PMID 28977985, 2017). "We conclude that the major mechanism used by Treg in the steady state is the regulation of CD80/CD86 expression and dysregulation of this suppressor pathway results in lethal autoimmunity driven by co‐stimulatory signals in concert with TCR stimulation, or even by costimulatory signals alone." (PMID 40346769, 2025). "Strikingly, gene-modified mice that cannot form the PD-L1/CD80 cis-heterodimer ameliorate anti-tumor T cell responses as well as autoimmunity, suggesting that the PD-1/PD-L1 inhibitory pathway is enhanced in the absence of the PD-L1/CD80 cis-heterodimer." (PMID 32787882, 2020). "It has been demonstrated that the expression of MHC molecules and the expression of costimulatory molecules such as B7-1 (CD80) and B7-2 (CD86) could modulate T cell activation and Th1/Th2 polarization during infection and autoimmunity." (PMID 23533995, 2013). "The authors hypothesize that CD80 is critical in maintaining immune tolerance through its interaction with the inhibitory receptor CTLA-4, which functions to modulate the immune response and prevent autoimmunity." (PMID 40725864, 2025). "Similarly, we also observed an increase in HLA-DR expression along with co-stimulatory molecules CD80 and CD86 in stimulated pDCs, suggesting that pDCs can efficiently present antigens to CD4 + T cells during autoimmunity and may contribute to the pathogenesis of T1D." (PMID 32483133, 2020).